RNU6-377P (RNA, U6 small nuclear 377, pseudogene)
Gene: Small nuclear RNA gene on chromosome 3 (12,514,706 to 12,514,807, forward strand). Ensembl gene ENSG00000251774.
Homologues: Orthologues: chimpanzee U6 (99% identical), macaque U6 (95% identical), pig U6 (84% identical), guinea pig U6 (82% identical), guinea pig U6 (76% identical), guinea pig U6 (74% identical). Paralogues in human: RNU6-43P (87% identical), RNU6-862P (86% identical), RNU6-1122P (85% identical), RNU6-11P (85% identical), RNU6-1251P (85% identical), RNU6-23P (85% identical), RNU6-379P (85% identical), RNU6-37P (85% identical), RNU6-97P (85% identical), RNU6-33P (84% identical), RNU6-774P (84% identical), RNU6-876P (84% identical), and 1287 more.